AGK (acylglycerol kinase)
Diseases named in the same sentence as AGK in open-access papers (continued):
Sharing a sentence is not in itself a finding about the gene and the disease.
tumor (continued). "AGK has been shown to be a significant cancer-related gene, which is overexpressed in multiple cancers and has been found to enhance the tumor-initiating ability of prostate cancer cells." (PMID 35934718, 2022). "Single-cell tumor sphere assays confirmed the higher frequency of sphere-initiating cells in overexpressed AGK cells." (PMID 35934718, 2022). "Compared to shRNA control group, BCL-2 expression was significantly increased in the tumor tissues from shRNA AGK group, and AS1842856 treatment abolished the enhanced expression of BCL-2." (PMID 35910796, 2022). "In the tumor tissues of AGK knockdown group, we found that the expression of BCL-2 was upregulated, but the phosphorylation of FOXO1 and AKT was significantly decreased." (PMID 35910796, 2022). "Through regulating the JAK2/STAT3/FOXM1 axis, in vivo tumor xenograft assays further demonstrated that knockdown of AGK inhibited tumor development and decreased resistance to paclitaxel." (PMID 36313702, 2022). "IHC results showed that the tumor areas with intense AGK staining revealed a high expression of Ki-67, whereas regions with weak AGK staining revealed a low expression of it." (PMID 35934718, 2022). "Inhibition of AGK also led to enhanced efficacy of venetoclax for suppression of DLBCL tumor growth in vivo, which was dependent on FOXO1." (PMID 35910796, 2022). "MiR-194 and miR-610 inhibit the proliferation and invasion of tumor cells by downregulating the expression of AGK, suggesting that AGK is an important downstream target of some miRNA mediated antitumor effects." (PMID 34368119, 2021). "Next, we will introduce the specific mechanism of AGK involved in tumor progression from the perspective of the AGK-regulated signaling pathway." (PMID 34368119, 2021). "AGK participates in the regulation of multiple signaling pathways during tumor occurrence and progression, which makes it a potential target for tumor therapy." (PMID 34368119, 2021). "In this paper, we comprehensively summarize the structure, function, and regulatory mechanism of AGK, focusing on its regulatory role in the tumor signaling pathway." (PMID 34368119, 2021). "The overexpression of AGK promotes angiogenesis and enhances the resistance of tumor cells to apoptosis by activating the NF-κB signal in hepatocellular carcinoma." (PMID 34368119, 2021). "Specifically, AGK has been identified as an oncogene that partakes in the regulation of tumor cell growth, invasion, metastasis, and drug resistance." (PMID 34368119, 2021). "An AGK‐BRAF fusion was newly identified in postmortem tumor specimens from a donor with a known EML4‐ALK fusion and resistance to ALK inhibitor therapy." (PMID 31747139, 2020). "IHC staining of paraffin-embedded archived biopsies further demonstrated that AGK was hardly observed in the adjacent normal tissues, while strong AGK expression was detected in the tumour tissues." (PMID 31900208, 2020). "YAP1 staining was mainly observed in the nuclei with little staining in the cytoplasm of tumour cells, whereas AGK was only observed in the cytoplasm of tumour cells." (PMID 32827244, 2020). "CCK‐8 assay data show that the rate of BGC‐823 cell proliferation was significantly higher in AGK‐overexpressing tumour cells than in the control, whereas the proliferation of HGC‐27 cells was reduced after knockdown of AGK expression." (PMID 32827244, 2020). "The Kaplan‐Meier curves and the log‐rank analysis revealed that the overall survival was lower in patients with high AGK‐expressing tumours than in the patients with low AGK‐expressing tumours l (53.8 ± 4.2 months vs 56.7 ± 3.2 months; P = .045)." (PMID 32827244, 2020). "Immunohistochemical analysis showed that the expression of AGK significantly correlated with patients’ clinicopathologic characteristics, including clinical stage and tumor-nodule-metastasis (TNM) classification." (PMID 24886245, 2014).
tumor (continued). "Given the significant role of AGK in tumor progression, defining the roles of AGK in TAMs may provide insights on how to further enhance the efficacy of immunotherapy." (PMID 39816692, 2025). "We detected the expression levels of MHC-II of TAMs in Agkfl/fl and AgkcKO LLC tumor tissues and found AGK deficiency promoted the expression of MHC-II, indicating AGK could suppress the transition of TAMs into the anti-tumor phenotype." (PMID 39816692, 2025). "Notably, the deletion of AGK in macrophages enhanced the suppressive effect on tumor growth when combined with PD-1 blockade therapy." (PMID 39816692, 2025). "Considering the pro-tumor effects of AGK in tumor cells and its ability to suppress the mtDNA-induced cGAS-STING pathway in macrophages, targeting AGK may offer a novel and promising strategy for enhancing immunotherapy in the context of cancer treatments." (PMID 39816692, 2025). "After 2~3 weeks, tumor volumes and tumor weights in AgkcKO mice were significantly reduced, compared to those in Agkfl/fl mice, indicating macrophage AGK may suppress macrophage anti-tumor activity in vivo." (PMID 39816692, 2025). "The tumor tissues with a high level of AGK staining revealed strong RPL39 signals." (PMID 35934718, 2022). "Interestingly, we found that the percentage of sphere-initiating cells increased with AGK, but primary-tumor spheres were only initiated in a subset of AGK-overexpressing cells." (PMID 35934718, 2022). "Similarly, Cox regression analysis revealed that tumor stage (P = 0.008), optimal cytoreductive surgery (P = 0.001) and an upregulated AGK (P = 0.05) were also independent prognostic factors for a poor OS." (PMID 35934718, 2022). "Expression of AGK in human tumor tissue compared with normal." (PMID 34368119, 2021). "Moreover, the abnormal expression of AGK in various types of tumors has been reported and is involved in many processes of tumor biology, such as proliferation, migration, metastasis, and even drug resistance." (PMID 34368119, 2021). "Since tumor prognosis is related to many factors, whether AGK can be used as a prognostic indicator of pan-cancer in the whole population remains to be supported by further clinical investigations and surveys." (PMID 34368119, 2021). "Additionally, a study of renal cell carcinoma and nasopharyngeal carcinoma found that AGK is involved in tumor progression and lymph node metastasis by activating the PI3K/Akt pathway." (PMID 34368119, 2021). "Interestingly, the protein levels of YAP1 and its target CTGF7 were down‐regulated in LV‐shAGK group, which further suggested that AGK depletion retards tumour growth by mainly inactivating YAP." (PMID 32827244, 2020). "AGK was markedly highly expressed in tumour tissues compared with adjacent normal tissues." (PMID 31900208, 2020). "In addition, the mean optical density (MOD) values of AGK staining significantly increased with progression of tumor stage from I to IV (P < 0.05)." (PMID 26443540, 2016). "Moreover, the prognostic value of AGK was analyzed when the patients were stratified according to tumor stage and T, N, and M classification." (PMID 26443540, 2016). "Taken together, these results confirmed that overexpression of AGK could contribute to the proliferation of tumor cells, indicating that AGK is involved in the progression of cancer." (PMID 26443540, 2016). "To further investigated whether AGK-deficient macrophages enhanced CD8+ T cell anti-tumor functions through type I IFN signaling, we blocked type I IFN signaling in vivo with anti-IFNAR antibody in the LLC tumor model." (PMID 39816692, 2025). "Furthermore, AGK modulates glycolysis in CD8+ T cells to influence tumor immunity." (PMID 39594764, 2024). "Acylglycerol kinase (AGK) is a newly discovered lipid kinase that has been reported to be a potent oncogene that may be involved in the regulation of malignant progression in a variety of tumours." (PMID 31900208, 2020).
tumor (continued). "Methods: siRNA was utilized to knock down the AGK gene; CCK8 and colony formation assays were employed to evaluate the in vitro proliferative capacity of tumor cells." (PMID 39594764, 2024). "To determine the relevance of AGK-mediated venetoclax sensitivity of DLBCL cells in vivo, we employed a widely used xenograft tumor model." (PMID 35910796, 2022). "In the present study, we found that AGK was upregulated in human EOC tissues, whose expression was significantly related to the poor clinicopathologic characteristics of EOC, including tumor stage, peritoneal cytology and the volume of ascites." (PMID 35934718, 2022). "Deletion of AGK impairs TCR-triggered metabolic reprogramming as well as the proliferation and anti-tumor function of CD8+ T cells." (PMID 35062950, 2022). "Statistical analysis showed a significant correlation between the expression of AGK and the clinicopathological characteristics of EOC, including tumor stage (P = 0.002), peritoneal cytology (P = 0.004) and the volume of ascites (P = 0.001)." (PMID 35934718, 2022). "Compared to the control group, the percentages of cytoplasmic FOXO1 positive cells were reduced in shRNA AGK group tumor tissues, while the nuclear localizations of FOXO1 were significantly enhanced in shRNA AGK group." (PMID 35910796, 2022). "In addition to tumor diseases, the roles of AGK in various systemic diseases remain unclear." (PMID 34368119, 2021). "By acting as a lipid kinase, AGK catalyzes the phosphorylation of acylglycerol to generate lysophosphatidic acid (LPA), which is known to be involved in tumor progression, invasion, neovascularization, and metastasis." (PMID 26443540, 2016). "Thus, we propose that AGK may have potential as target for therapy in a range of tumor types." (PMID 25474138, 2014). "On one hand, AGK promotes angiogenesis and inhibits apoptosis in liver cancer cells through the activation of NF-κB; on the other hand, it activates the PI3K/AKT/GSK3β signaling pathway, facilitating tumor onset, proliferation, and metastasis in renal cancer." (PMID 39594764, 2024). "The expressions of AGK, BCL-2 and FOXO1 were evaluated in tumor tissues of DLBCL patients." (PMID 35910796, 2022). "Other low frequency actionable fusions namely, AGK-BRAF, FIP1L1-PDGFRA, FNDC3B-PIK3CA, RET-NCOA4, SND1-BRAF, TMEM178B-MET, TMEM178B-BRAF, KANK1-NTRK3, EIF3E-RSPO2 and PTPRK -RSPO3 have been previously reported as rare fusions in tumours of other type." (PMID 35984852, 2022). "Through the data analysis results of the relevant data of the protein atlas database, we found that the high expression of AGK does not seem to predict the prognosis of tumor patients." (PMID 34368119, 2021). "The oncogenic effects of AGK in human RCC progression were investigated using assays of colony formation, anchorage-independent growth, EdU assay, cell cycle analysis, wound-healing, trans-well analysis and xenograft tumour model." (PMID 31900208, 2020). "Notably, the case featuring the AGK–BRAF fusion stands out, with an exceptional tumor response to belvarafenib in a patient who might otherwise be ineligible for such clinical trials due to their young age." (PMID 38470950, 2024). "AGK (Acylglycerol kinase) is a positive regulator of CD8+ T cells glycolysis (glucose metabolism) which is a prerequisite for effector CD8+ T cells proliferation and activity, while CD8+ T cells play a pivotal role in adaptive anti-tumor immunity to eliminate cancer cells." (PMID 36109471, 2023). "Indeed, AGK is an enzyme of lipid kinase property that is involved in the conversion of acylglycerol to lysophosphatidic acid (LPA) through phosphorylation and also regulates tumor expansion." (PMID 36109471, 2023). "To investigate whether the expression of AGK could be a biomarker for predicting the response to venetoclax in DLBCL patients, we performed H&E and BCL-2 immunohistochemical staining for human DLBCL primary tumor tissues of 33 individual patients." (PMID 35910796, 2022).
tumor (continued). "On the other hand, the absence of AGK in CD8+ T cells showed the impairment of glycolysis and effective anti-tumor functions in vivo and in vitro respectively." (PMID 36109471, 2023).
cancer (19 papers, 2014 to 2026). A tumor composed of atypical neoplastic, often pleomorphic cells that invade other tissues. "Recent evidence has demonstrated that dysregulated AGK expression is associated with the development of various human cancers." (PMID 32827244, 2020). "While some studies have indicated that high AGK expression is associated with a poor prognosis for patients with certain types of cancer, AGK may be used to identify the risk of patients and guide personalized treatment." (PMID 34368119, 2021). "AGK has been widely reported to act as an oncogene in various cancers by regulating metabolism and mitochondrial function." (PMID 39254643, 2024). "AGK also promotes the growth of renal cell carcinomas and exacerbates cancer progression via activating the PI3K/AKT/GSK3β signaling pathway." (PMID 35934718, 2022). "As an effective oncogene, AGK is involved in the occurrence and development of a variety of cancers." (PMID 34368119, 2021). "Inhibiting its expression in certain cancer cells has led to anticancer effects, indicating that AGK is a potential therapeutic target in a variety of cancers." (PMID 34368119, 2021). "Overexpression of AGK can drive cancer cell growth and play an important role in pathophysiology of cancer." (PMID 28573829, 2017). "Another enzyme produced by some cancer cells that can generate LPA is acylglycerol kinase, which acts on the monoacylglycerol in plasma." (PMID 27571113, 2016). "Several reports have also provided evidence that AGK is involved in the survival and motility of malignant phenotypes of cancer cells and the development of cancer stem cells." (PMID 24886245, 2014). "Analysis of cancer patient survival correlated with AGK expression." (PMID 34368119, 2021). "We believe that AGK is a promising target for cancer therapy." (PMID 34368119, 2021). "Aberrant YAP1 and AGK expressions have been reported in various human cancers." (PMID 32827244, 2020). "Indeed, several previous studies have demonstrated an oncogenic role of AGK in various types of human cancer." (PMID 32827244, 2020). "Taken together, these findings indicate that AGK may play an essential role in the progression and development of cancer." (PMID 26443540, 2016). "In prostate cancer patients, the extent to which their cancers expressed autotaxin, but not acylglycerol kinase, correlated positively with risk for biochemical recurrence following surgery." (PMID 27571113, 2016). "Combined with the results of our study that AGK expression is elevated in HCC, we may infer that the upregulation of AGK could be a marker for cancerous state and may serve as a universal prognostic factor for cancer." (PMID 25474138, 2014). "For example, in oral squamous cell carcinoma, miR-194 can inhibit the PI3K/Akt/FOXO3a signaling pathway by inhibiting AGK, resulting in the decreased expression of cyclin D1 and the increased expression of P21, which ultimately inhibits the proliferation and cell cycle progression of cancer cells." (PMID 34368119, 2021). "Therefore, targeted inhibition of AGK may be a favorable strategy for anti-angiogenesis and pro-apoptotic cancer therapy." (PMID 34368119, 2021). "In addition, AGK expression has also been reported to be upregulated in cancer." (PMID 26176541, 2015). "Machine learning models based on seven LM-related genes (CHEK2, LIPT1, TUFM, NDUFA10, AGK, PNPLA2, and GFM1) accurately predicted immunotherapy outcomes for multiple cancer types, including LUSC, and outperformed other currently known biomarkers." (PMID 40568577, 2025). "Our study provided important experimental evidence that RPL39 was an EOC-CSCs-related gene involved in cancer progression, chemoresistance and CSC formation by directly interacting with AGK in mitochondria." (PMID 35934718, 2022). "The overexpression of AGK can reduce the activation of FOXO1 activity and its downstream targets, thereby enhancing the proliferation and tumorigenicity of cancer cells." (PMID 34368119, 2021).
cancer (continued). "Therefore, AGK, as an oncogene, may become a potential target for cancer treatment." (PMID 34368119, 2021). "However, the clinical value of AGK in cancer remains unclear." (PMID 26443540, 2016). "Acylglycerol kinase (AGK) has been reported to promote a malignant phenotype and enhance the development of cancer stem cells." (PMID 26443540, 2016). "This study not only further elucidates the precise role of AGK in the pathogenesis of HCC, but also provides new insight into the biological basis of cancer progression and may help to identify more effective therapeutic strategies for HCC." (PMID 25474138, 2014). "Acylglycerol kinase (AGK) was originally identified as a multisubstrate lipid kinase, and catalyzes the phosphorylation of acylglycerols to generate lysophosphatidic acid (LPA), thus regulating multiple cellular processes related to pathogenesis of cancer." (PMID 25474138, 2014).
mitochondrial disease (2 papers, 2022). "Two subunits of the TIMM22 complex are currently connected to mitochondrial disease: the pore subunit TIMM22, and the receptor subunit AGK (acylglycerol kinase)." (PMID 36475414, 2022).
metabolism disorders (1 paper, 2022). "The critical role of AGK in oxidative phosphorylation suggested that the absence of AGK leads to glucose metabolism and amino acid metabolism disorders." (PMID 35547757, 2022).
AGK also shares sentences with these, for which no sentence is quoted: hypertrophic cardiomyopathy (7 papers); myopathy (3); cardiomyopathy (2); cervical squamous cell carcinoma (2); diffuse large B-cell lymphoma (2); thyroid cancer (2); acute myeloid leukemia (1); adenocarcinomas of the colon (1); Barth syndrome (1); Bladder Urothelial cancer (1); diabetic retinopathies (1); esophageal cancer (1); heart failure (1); hyperopia (1); infection (1); kidney cancer (1); liver dysfunction (1); Lung squamous cell cancer (1); lymphoma (1); malaria (1); myoepithelial carcinoma (1); myopia (1); Obesity (1); Papillary Thyroid Carcinoma (1); proliferative diabetic retinopathy (1); rectum adenocarcinoma (1); Small lymphocytic lymphoma (1); thyroid tumor (1).